RNU6-62P (RNA, U6 small nuclear 62, pseudogene)
Synonyms: RNU6-62
Gene: Small nuclear RNA gene on chromosome 13 (95,019,235 to 95,019,336, forward strand). Ensembl gene ENSG00000252335.
Homologues: Orthologues: macaque U6 (93% identical), mouse Gm25792 (69% identical), rabbit U6 (69% identical), dog U6 (67% identical), guinea pig U6 (67% identical), rat LOC120103222 (55% identical). Paralogues in human: RNU6-116P (73% identical), RNU6-959P (72% identical), RNU6-103P (71% identical), RNU6-1103P (71% identical), RNU6-1292P (71% identical), RNU6-14P (71% identical), RNU6-17P (71% identical), RNU6-182P (71% identical), RNU6-18P (71% identical), RNU6-238P (71% identical), RNU6-268P (71% identical), RNU6-33P (71% identical), and 1288 more.